SRC (SRC proto-oncogene, non-receptor tyrosine kinase)
Diseases named in the same sentence as SRC in open-access papers (continued):
Sharing a sentence is not in itself a finding about the gene and the disease.
breast cancer (continued). "Further, nicotine was found to promote proliferation and invasion in 2 human breast cancer cell lines (MCF7, MDA-MB-468) through a nAChR, SRC and calcium-dependent signaling pathway." (PMID 33203443, 2020). "Instead, we show that GTPase-activating protein GIT ArfGAP 1 (GIT1) is an SRC effector that regulates YAP/TAZ activity in both melanoma and breast cancer cells." (PMID 30559289, 2019). "SRC inhibition reduced YAP/TAZ activity in the majority (25 of 28) of human and mouse melanoma and breast cancer cell lines that we tested." (PMID 30559289, 2019). "We revealed a new SRC effector protein that regulates YAP and TAZ in breast cancer and melanoma cells." (PMID 30559289, 2019). "Our results show that inhibition of SRC represses YAP/TAZ transcriptional activity in the majority of human melanoma and breast cancer cell lines that we tested." (PMID 30559289, 2019). "It has been reported that SRC is activated and regulates tumorigenesis through phosphorylation of ETS-1 in breast cancer." (PMID 31118072, 2019). "Expression of a constitutively active SRC mutant (SRCY527F) promoted YAP/TAZ transcriptional activity in the majority of the cell lines we tested, including several human and mouse breast cancer and melanoma cell lines." (PMID 30559289, 2019). "Together, these results show that SRC is required for YAP/TAZ activity and target gene expression in many breast cancer and melanoma cell lines." (PMID 30559289, 2019). "As we observed in the melanoma cells, knockdown of SRC significantly inhibited YAP/TAZ activity and reduced metastatic burden in these breast cancer cells." (PMID 30559289, 2019). "This notion was supported by the fact that invasiveness of human breast cancer cells MCF-10A transduced with oncogenes; Neu-T, H-RAS or c-SRC increased in response to CCL516." (PMID 29358632, 2018). "BRC-31 cells display elevated focal adhesion kinase (FAK), SRC and extracellular signal-regulated (ERK2) phosphorylation relative to luminal breast cancer models." (PMID 29382358, 2018). "The kinases SRC and FAK are generally involved in cancer cell adhesion and invasion, including in breast cancer cells." (PMID 25871389, 2015). "Our NMF analysis based on phosphorylation status of SRC, ERK and AKT also showed that butein-resistant luminal HER2+ breast cancer cell lines were categorized in the same hierarchical cluster." (PMID 24919544, 2014). "The p160 steroid receptor coactivator (SRC) family contains three members, SRC-1, SRC-2/GRIP1/TIF2 and SRC-3/Amplified in Breast Cancer-1 that interact with multiple nuclear receptors (NRs) and other transcription factors to regulate gene transcription." (PMID 24743578, 2014). "In our screen of additional breast cancer cell lines, the LOF of SRC enhanced TRAIL-induced caspase-3/7 activation by 2 or more standard deviations in the two TNBC cell lines MB231 and MB468, and by 1 standard deviation in the ER-positive cell line T47D." (PMID 24745479, 2014). "Further, we confirmed that small-molecule inhibition of SRC or BCL2L1, in combination with TRAIL, sensitizes breast cancer cells to TRAIL-induced apoptosis, including cell lines resistant to TRAIL-induced cytotoxicity." (PMID 24745479, 2014). "We also report that a highly specific AHR agonist significantly (P < 0.05) inhibits the expression of E2F1, CCND1 (known as Cyclin D1), MYB, SRC, JAK2, and JUND in breast cancer cells." (PMID 24171117, 2013).
breast cancer (continued). "Katz has reported that activation of AKT by CDDP is dependent of SRC, EGFR and PI3K, which can be placed in one signal transduction pathway, with EGFR and SRC upstream of PI3K in breast cancer." (PMID 23533654, 2013). "In addition, distinct PTMs of the SRC members play a crucial role in controlling their intracellular levels and functions, which may have significant impact on breast carcinogenesis and response to endocrine treatment in breast cancer patients." (PMID 23936147, 2013). "The results show that a number of important cancer genes for each cancer type are ranked highly by TARGETgene, such as AKT1 (rank #1), SRC (rank #10), and ERBB2 (rank #25) in breast cancer." (PMID 22952662, 2012). "We have reported a longer latency until appearance of mammary tumors in MMTV-PyVT mice, and depressed activation of SRC, in the context of a Nedd9−/− versus a Nedd9+/+ genotype." (PMID 21765937, 2011). "The hub targets identified for SRC, PIK3R1, PIK3CA, STAT3, and EGFR may represent significant therapeutic targets for the treatment of breast cancer using TSAC." (PMID 40864816, 2025). "To evaluate the underlying mechanisms by which SDC3 influences cell viability, cell-cycle regulation, stemness, and migration in breast cancer, we investigated the effects of SDC3 depletion on the activation of proto-oncogene tyrosine-protein kinase Src (pSRC, SRC)." (PMID 41148827, 2025). "According to the RT-qPCR results, the hub genes SRC, PIK3CA, and EGFR may be involved in the anti-breast cancer effects of TSAC." (PMID 40864816, 2025). "Though calycosin can decrease the phosphorylation levels of SRC, EGFR, ERK1/2, and Akt in breast cancer lines and meningitis, its role in chondrocytes remains unclear." (PMID 38254101, 2024). "TGFB2, and other proteins in this pathway (SRC, AKT, ERK2, and a Slug interactor called LSD1) all maintain the stability of Slug, meaning that Slug levels remain high and drive the aggressive features of this subtype of breast cancer." (PMID 39327614, 2024). "For the same reason, we did not consider the strongly increased level (+130%) of SRC, a tyrosine kinase engaged in breast cancer development and progression, which was observed only in cells exposed to High-Glc DMEM." (PMID 39329717, 2024). "SRC, a non-receptor tyrosine kinase, is an oncogene activated in epithelial tumor entities such as colon and breast cancer." (PMID 38847867, 2024). "Interestingly, targeting c-SRC has been reported to be effective in overcoming resistance to trastuzumab, one of the FDA-approved HER2 targeting drugs in breast cancer treatment." (PMID 37759706, 2023). "Finally, we show that PTK6 and SRC are coexpressed in subsets of human prostate and breast cancer cells, and active PTK6 and active SRC colocalize in prostate cancer, supporting a role for PTK6 in promoting SRC activity in cancer." (PMID 36228719, 2022). "Furthermore, hypoxia-induced upregulation of VEGF is mediated by the activation of SRC, and its knockdown using RNAi attenuated VEGF expression in breast cancer cells." (PMID 35273218, 2022). "Cell cycle profiling of breast cancer cell lines treated with a range of AZD0424 concentrations for 24 h revealed, at best, a modest G1‐arrest at concentrations > 1 μm and which is in agreement with other SRC inhibitors such as saracatinib or dasatinib." (PMID 34856074, 2022). "The analysis of the breast cancer scRNAseq dataset shows that PTK6 and SRC are highly expressed in cells from all cancer types (basal, cycling, HER2+, Luminal A, and Luminal B) with a high correlation between PTK6 and SRC expression in these cells." (PMID 36228719, 2022). "In MCF7 breast cancer cells, TN-C induced EMT-like morphological changes, which, on a molecular level, included the delocalization of E-cadherin and β-catenin correlating with tyrosine-protein kinase SRC activation and the SRC-mediated phosphrorylation of FAK." (PMID 35785162, 2022).
breast cancer (continued). "Because of its established roles in prostate and breast cancer, we explored how PTK6 and SRC are coexpressed in nonmalignant and malignant prostate and breast cancer tissues." (PMID 36228719, 2022). "SRC is a non-receptor tyrosine kinase, participating in several oncogenic pathways and promoting tamoxifen resistance in breast cancer." (PMID 36142451, 2022). "Moreover, NCAPG has been shown to modulate the SRC/STAT3 signaling pathway and confer resistance to trastuzumab in HER2-positive breast cancer cells." (PMID 35280743, 2022). "The top 20 possible drugs that could reverse the breast cancer lung metastasis signature were presented, including IGF-1 inhibitor, mTOR inhibitor, PI3K inhibitor, SRC inhibitor, aurora kinase inhibitor, and JAK inhibitor." (PMID 35111673, 2021). "Moreover, the tyrosine 40 in the LIR domain of paxilin is a target of the SRC kinase, and constitutively, active SRC strongly increased the LC3B–paxilin interaction and migration in breast cancer cells." (PMID 34207792, 2021). "Slight association between reduced OCLN expression and poor overall survival was observed in a cohort with 10-year follow-up of breast cancer patients, and studies conducted on human cell lines demonstrated that OCLN phosphorylation by SRC attenuates its assembly at the tight junctions." (PMID 33450402, 2020). "In addition, Src (SRC), VEGFR2 (KDR), IGF1R and PI3Kγ (PIK3CG) have already been successful targets in breast cancer therapy." (PMID 33246450, 2020). "More important, breast cancer cells expressing ectopic or endogenous ESR1-CCDC170 are highly sensitive to treatment regimens combining endocrine agents with the HER2 inhibitor lapatinib and/or the SRC inhibitor dasatinib." (PMID 32771039, 2020). "In addition to p42/44MAPK, CCL2/CCR2 activates multiple signaling pathways in breast cancer cells including: PKC, Rho and SRC to regulate growth and motility." (PMID 31208996, 2019). "Together, these findings suggest that SRC, EGFR, ERK1/2, and Akt, which are key regulators of cell proliferation and survival in breast cancer cells, act as downstream effectors of the WDR7-7-GPR30 pathway, especially in ER− cells due to the absence of an ER-mediated pathway." (PMID 29096683, 2017). "SRC (PP2), AKT and ERK/MEK (UO126) inhibitors provoked a clear decrease in the invasive and transendothelial migration capacity of scrambled melanoma and breast cancer transfectants, similar to those achieved by VE-cadherin-silenced counterparts." (PMID 27966446, 2017). "For example, in ER− breast cancer cells, GPR30 activates the tyrosine kinase SRC through the Gβγ subunit, which stimulates the autophosphorylation of EGFR to initiate MAP-kinase ERK1/2 and phosphatidylinositol 3 kinase (PI3K) signaling, ultimately inducing proliferation." (PMID 29096683, 2017). "We reviewed the functional properties of the driver nodes found to have the highest impact in controlling the essential proteins; they are ERBB2, SRC, PDPK1, PRKDC, mTOR for breast cancer, ERBB2, AKT1, GSK3B, ABL1 in pancreatic cancer, and RET in ovarian cancer." (PMID 28871116, 2017). "For the other top-ranked miRNAs, five have no validated targets but have many predicted targets related to breast cancer such as AKT, AKT1, CCND1, EGFR1, ERBB2, SRC, PTEN which have been used as breast cancer biomarkers for prognosis, diagnosis, drug efficacy, and disease progression." (PMID 27833082, 2016). "KX2-391 is currently also being tested for breast cancer treatment (NCT01764087) and our finding of the SL relationship between EPHB6 and SRC indicated that KX2-391 treatment may work more efficiently if applied specifically to EPHB6-deficient TNBC cells." (PMID 27418135, 2016). "Ectopic expression of TLK2 leads to enhanced aggressiveness in breast cancer cells, which may involve the EGFR/SRC/FAK signalling." (PMID 27694828, 2016).
breast cancer (continued). "Taken together, these data suggest that EGFR/SRC/FAK axis may be important in TLK2-driven invasiveness in breast cancer cells, and TLK2 may engage this axis via interaction with SRC." (PMID 27694828, 2016). "Importantly, this study demonstrates that phenocopying SRC and BCL2L1 LOF by pharmacologic inhibition can sensitize TRAIL-resistant breast cancer cell lines to TRAIL-induced apoptosis." (PMID 24745479, 2014). "When cells were treated with different doses of butein for 15 minutes, butein did not uniquely affect phosphorylation of either SRC or ERK in different breast cancer cells, while butein inhibition of SRC has been revealed." (PMID 24919544, 2014). "Based on our siRNA studies, the LOF of SRC may potentially represent a context-specific modulator of TRAIL activity, whereas LOF of BCL2L1 may modulate TRAIL activity in a broader range of breast cancer cell types." (PMID 24745479, 2014). "In the present study we showed that SRC is a key node of TRAIL-induced apoptosis, as illustrated in the pathway-analysis map, and that inhibition of SRC by PP2 increases the sensitivity of breast cancer cells to TRAIL." (PMID 24745479, 2014). "We propose that SDC3 may regulate the activity of the proto-oncogene tyrosine-protein kinase Src (SRC) in the context of the TF pathway, as well as other genes involved in crucial breast cancer signaling pathways, thereby affecting human breast cancer cell behavior." (PMID 41148827, 2025). "In addition to its role of immunosuppression via regulating PD-1 expression in macrophages surrounding breast cancer cells, CCL2 may also influence breast cancer cell proliferation and cell-cycle progression through SRC and PKC activation." (PMID 39703847, 2024). "We conclude that this SRC-Slug-TGFβ2 axis may contribute to chemotherapy resistance in an aggressive subpopulation of TNBC tumors, and targeting this pathway may help to improve outcomes for this aggressive breast cancer subtype." (PMID 39327614, 2024). "Notably, TCGA analysis revealed that SRC was, on average, 1.8-fold overexpressed in patient-derived tissues; however, SRC was not overexpressed in various breast cancer cell lines compared to the level seen in the normal breast epithelial cell line MCF10A." (PMID 37439249, 2023). "Previous studies on lung, gastric, cervical, and breast cancers have shown that miR-150-5p promotes cell proliferation and migration by targeting the SRC kinase signaling inhibitor 1 (SRCIN1), a negative regulator of SRC and an experimentally validated direct target of miR-150-5p." (PMID 35565284, 2022). "Therefore, SRC and NOS3 play an important role in the progression of breast cancer." (PMID 36016606, 2022). "In addition, the extranuclear complex of ERα:SRC:PLCγ (phospholipase Cγ) plays a role in activation of the tumor-protective anticipatory UPR (unfolded protein response) (UPR), thereby increasing the resilience of breast cancer cells." (PMID 33503805, 2021). "CRIPTO’s effects on breast cancer cells are likely mediated by its joint modulation of the TGF-β pathway and growth factor-like signaling (i.e., activation of SRC/MAPK/PI3K pathways), and there may also be important roles for other pathways regulated by CRIPTO including WNT and NOTCH." (PMID 33187540, 2020). "Furthermore, (+)-aeroplysinin-1 from sponge displays a strong antitumor effect by blocking the proliferation of EGFR-dependent human breast cancer cell lines MCF-7 and ZR-75-1, while curcuphenol displays a SRC protein kinase inhibition and curcudiola focal adhesion kinase (FAK) inhibition." (PMID 29320389, 2018). "As to TGFβ receptor signaling, it has been shown that c-SRC can phosphorylate TGFβ type II receptor directly at Tyr284 and this controls the TGFβ-driven activation of p38 MAPK and induction of EMT, which in turn lead to a promotion of proliferation and invasion in breast cancer cells." (PMID 26849234, 2016).
breast cancer (continued). "In breast cancer, PTEN deficiency has been shown to activate, in a manner dependent on its protein phosphatase activity, the SRC proto-oncogene, non-receptor tyrosine kinase (SRC), thereby conferring resistance to human epidermal growth factor receptor 2 inhibition." (PMID 26655726, 2015). "However, ETS-2 has also been implicated in prostate cancer and together with other factors including ETS-1, SRC-1 (v-src avian sarcoma [Schmidt-Ruppin A-2] viral oncogene homolog), AIB-1 (nuclear receptor coactivator 3) and NcoR (nuclear receptor co-repressor), breast cancer." (PMID 18958307, 2008). "Interestingly, blocking the SRC/EGFR-dependent ITGB4/FAK pathway, which subsequently inactivates the Akt and p38/MAPK pathways contributes to the suppression of migration and invasiveness of breast cancer cells and reversal of EMT process after treatment with Ziyu II." (PMID 35379785, 2022). "Other genes, including ATP5A, BCR, FGFR4, PDPK1, PIP5K1C, RIOK3, and SRC, also act to regulate TRAIL-induced apoptosis, but their potential to overcome resistance to TRAIL-induced cytotoxicity when inhibited may be more context specific (that is, in a more-restricted subset of breast cancer cells)." (PMID 24745479, 2014). "Here, we show that SRC proto-oncogene, nonreceptor tyrosine kinase (SRC) is an important driver of YAP/TAZ activity in human breast cancer and melanoma cells." (PMID 30559289, 2019). "Importantly, positive correlations between immuno-enriched SRC protein and G6PD Y249/322 phosphorylation specifically manifest in ER/PR positive or HER negative types of breast cancer." (PMID 37491277, 2023). "ER may interact with SRC (non-receptor tyrosine kinase) out of the nucleus to activate extranuclear signaling pathways, such as ERK1/2 and AKT, in breast cancer cells." (PMID 33503805, 2021). "Another major pathway involved in the proliferation of breast cancer cells is the MAPK pathway, which is involved particularly via a rapid and transient interaction between ERα and the intracellular SRC proto-oncogene, non-receptor tyrosine kinase (c-Src/Src)." (PMID 30678243, 2019). "While butein has been revealed to affect SRC via direct interactions, we could not find common inhibitory effects of butein on SRC or its downstream ERK in various breast cancer cell lines." (PMID 24919544, 2014). "In contrast, in the low invasive/nonmetastatic breast cancer cell line T47D, which had no detectable MET and CDCP1 expression, ectopic MET expression stimulated the HGF-dependent activation of invasive activity, and concomitant CDCP1 expression activated SRC and further promoted invasive activity." (PMID 35085554, 2022).